ACSS2 (acyl-CoA synthetase short chain family member 2)
Diseases named in the same sentence as ACSS2 in open-access papers (continued):
Sharing a sentence is not in itself a finding about the gene and the disease.
tumor (121 papers, 2013 to 2026). "To further elucidate the influence of ACSS2 knockdown on autophagic flux in in - vivo experiments, we employed Western Blot to detect the expression levels of autophagy-associated proteins in tumor tissues." (PMID 40858538, 2025). "A growing body of research indicates that hypoxia causes ACSS2 expression, which aids tumour cells in surviving in this nutrient-poor environment and promotes tumour growth, proliferation, invasion, and metastasis." (PMID 40287570, 2025). "Oncogenic KRAS mutations synergize with ACLY and ACSS2 enzymatic activities to drive tumor cell proliferation and metastatic progression." (PMID 40814339, 2025). "Under metabolic stress conditions, ACSS2 promotes the growth of cancer cells, and ACSS2 deficiency inhibits the growth of tumor cells and tumor formation in mice." (PMID 38263056, 2024). "This article focuses on targeting the metabolic enzyme ACSS2, which has been implicated as a key regulator of tumor growth in the brain." (PMID 38818373, 2024). "Silencing ACSS2 caused significant inhibition of spheroid formation and markedly reduced xenograft tumor growth derived from breast and prostate cancer cells." (PMID 38060103, 2023). "In GB, higher expression levels of ACSS2 are associated with higher tumor grade and lower survival rates." (PMID 37298093, 2023). "An Acyl-CoA Synthetase Short Chain 2 (ACSS2) deficient mouse model was used to examine the role of this enzyme in tumor growth." (PMID 36597205, 2023). "TIMER database analysis showed that ACSS2 expression in CESC was associated with tumor infiltration of B cells, CD4+ and CD8+ T cells, and cancer-associated fibroblasts (CAF)." (PMID 34206705, 2021). "The immune microenvironment plays a key role in both tumor progression and elimination; therefore, it is interesting to analyze the association between ACSS2 expression and pro-/anti-tumor immune components." (PMID 34206705, 2021). "Because macrophages are the immune cell type most closely associated with ACSS2 expression, we further investigated the association between ACSS2 and the immune marker set of monocytes, tumor-associated macrophages (TAM), M1 macrophages, and M2 macrophages." (PMID 34206705, 2021). "To understand the genetic changes in the ACSS family, we found that 2.4% of the ACSS2 gene was mutated in various cancers by querying the copy number change data and mutation percentage of various tumor samples recorded in cBioportal." (PMID 34206705, 2021). "For instance, studies have shown that targeted inhibition of ACSS2-mediated acetyl-CoA synthesis caused growth inhibition of cultured tumor cells and significantly reduced the growth and size of tumor xenografts in mice." (PMID 30992471, 2019). "ACSS2 expression is also associated with increased tumor aggressiveness in patients with cancer, and hypoxia-induced lipid metabolism reprogramming results in fatty acid accumulation, which, upon reoxidation, promotes tumor growth and survival." (PMID 38544822, 2024). "Furthermore,ACSS2 deficiency in mouse models of hepatocellular carcinomahas been shown to reduce tumor burden and inhibittumor growth." (PMID 39944803, 2024). "ACSS2 has also been implicated in regulating acetate-dependent lipid synthesis in tumor cells." (PMID 25689462, 2015). "In addition, ACSS2 facilitates the consumption of extracellular acetate as an alternative carbon source and leads to lipid deposition, causing an inflammatory response in tumor cells." (PMID 36982619, 2023). "In ATCs, ACSS2 was the only upregulated gene, suggesting further tumor adaptation to the metabolic stress of rapidly growing cancers." (PMID 41752148, 2026). "Research on tumours has demonstrated that, in response to metabolic stress, cancer cells activate or upregulate the expression of ACSS2 to adapt to the growth conditions in the tumour microenvironment (TME)." (PMID 40287570, 2025).
tumor (continued). "In tumor cells, ACSS2 expression can be upregulated to enhance acetate uptake, replacing the carbon supply for lipid metabolism under stressful conditions with hypoxia and low glucose supply." (PMID 40097417, 2025). "Numerous tumours, such as glioblastoma, breast cancer, liver cancer, prostate cancer, and others, have high expression levels of ACSS2." (PMID 40287570, 2025). "Manders’ overlap coefficient (MOC) quantified that ACSS2 and sFasL exhibit compartmentalized co‐localization specifically in tumor epithelial cells." (PMID 40791180, 2025). "Numerous investigations have demonstrated that ACSS2 knockdown can prevent the growth of a range of malignancies because ACSS2 is necessary for the development of tumour cells in hypoxia and energy stress." (PMID 40287570, 2025). "By comparing the clinicopathological characteristics of patients with HNSCC with the ACSS2 expression levels, it can be known that patients with high ACSS2 expression presented with later tumor stages and extended lymph node metastases." (PMID 40858538, 2025). "Acetyl-CoA Synthetase 2 (ACSS2) has emerged as a new target for anticancer development owing to its high expression in various tumours and its enhancement of malignancy." (PMID 40287570, 2025). "Several enzymes involved in de novo fatty acid synthesis, including FASN, ACLY, SCD, and ACSS2, are abnormally expressed in various cancers, promoting fatty acid synthesis and contributing to malignant tumor phenotypes." (PMID 41285764, 2025). "Previous studies have demonstrated that tumor cells adapt to the TME by activating or increasing the expression level of ACSS2 under metabolic stress." (PMID 40908872, 2025). "Considering the critical role of autophagy in tumor cell function, we further investigated the effect of ACSS2 KD on autophagic flux in HNSCC cells." (PMID 40858538, 2025). "ACSS2 (Acyl-coenzyme A synthetase short-chain family member 2), a gene found to be central to acetate metabolism in brain and other tumours, was found to be highest in IMD lesions." (PMID 39915301, 2025). "Under hypoxia, tumor cells convert acetate to acetyl-CoA via ACSS2, activating lipogenic genes (e.g., FASN) to fuel de novo lipogenesis and support growth." (PMID 40718481, 2025). "Studies have shown that ACSS2, which is often upregulated in some tumors, participates in the metabolic rewiring of tumor cells in order to maintain acetyl-CoA levels." (PMID 40863614, 2025). "ACSS2 expression is abnormal and specific to a variety of tumors, and is closely related to tumor occurrence, development, and prognosis." (PMID 40858538, 2025). "The Warburg effect, marked by elevated glycolysis, supports rapid tumor growth, with acetylation modulating key metabolic enzymes like ACSS2." (PMID 41029427, 2025). "ACSS2 provides acetyl-CoA to tumor cells via glucose-derived endogenous acetate in these cells and is a potential target for cisplatin resistance." (PMID 41281744, 2025). "Conversely, CD8+ T cells utilize acetate in an ACSS2-dependent manner to rescue effector functions impaired by glucose deprivation, highlighting acetate’s paradoxical roles in tumor progression." (PMID 40718481, 2025). "This metabolite‐epigenetic‐immune cascade promotes tumor immune evasion, thereby establishing ACSS2/AATF as a synergistic molecular nexus for targeted PNET immunotherapy." (PMID 40791180, 2025). "In this regard, significant research efforts have been allocated to inhibiting ACSS2-mediated acetate production, ultimately potentiating tumour growth and survival." (PMID 40287570, 2025). "Subcutaneously inject shACSS2/NC CAL27 and SCC9 cells into mice, and the results showed that ACSS2 knockout had a significant inhibitory effect on the volume of transplanted tumors, indicating that ACSS2 knockout inhibited tumor growth." (PMID 40858538, 2025). "Herein, this study identifies the ACSS2/AATF axis as a compartment‐specific regulator of sFasL—a bridge coupling tumor metabolic reprogramming to CD8+ T cell exhaustion." (PMID 40791180, 2025).
tumor (continued). "ACSS2 is a lipid metabolism enzyme that not only promotes the metabolism of tumor cells by converting long-chain fatty acids to the active form of acyl-CoA, but also participates in autophagy regulation." (PMID 40858538, 2025). "Zachary T. Schug and his team synthesized VY-3-135, a small molecule that demonstrated good specificity for ACSS2 with tumour growth suppression both in vitro and in vivo experiments conducted on mice and human breast models." (PMID 40287570, 2025). "The results surfaced that ACSS2 expression was higher in pNENs tumor tissues than in paraneoplastic tissues." (PMID 38263056, 2024). "Animal experiments were further performed to investigate the influence of ACSS2 on tumor growth and metastasis in vivo." (PMID 38887280, 2024). "Cancer growth dependence on ACSS2 has been previously demonstrated in tumors where reduced tumor burden was shown in ACSS2-/- and shACSS2 models." (PMID 38851813, 2024). "Taken together, these data suggest treatment with AD-8007 can significantly reduce BCBM tumor burden and extend survival in vivo, futher validating our novel ACSS2 inhibitors as possible canidates for the treatment of BCBM patients." (PMID 38818373, 2024). "Overexpression of HMGCS1 can reverse the enhanced lipid metabolism reprogramming and tumor-promoting effects of knockdown of ACSS2." (PMID 38263056, 2024). "Reduction of preformed tumors by our novel ACSS2 inhibitors was similar to the effects of treatment of tumor bearing brain slices with VY-3-135." (PMID 38818373, 2024). "Tumor weight and volume were smaller in the knockdown of ACSS2 group compared to the wild-type group, and further larger in the overexpression of HMGCS1 in ACSS2 knocked down group compared to the knockdown of ACSS2 group." (PMID 38263056, 2024). "The findings revealed that ACSS2 depletion led to a significant reduction in tumor growth, as evidenced by decreased tumor volume and weight compared to the control group." (PMID 38887280, 2024). "The acetyl-CoA synthetase short-chain family member 2 (ACSS2) generates acetyl-CoA from acetate to support tumor growth, the biosynthesis of cholesterol, glucose and fatty acid, as well as ketogenesis and protein acetylation." (PMID 38332049, 2024). "Zachary’s research group established that in the context of glucose deprivation, acetate catalyzes histone acetylation in tumor-infiltrating CD8+ T cells via an ACSS2-dependent pathway, consequently augmenting IFN-γ production." (PMID 38887280, 2024). "Deleting ACSS2 in tumor cells results in a switch from acetate consumption to acetate production by tumor cells, thereby increasing acetate as a fuel source for tumor-infiltrating CD8+ T cells and enhancing T cell proliferation and effector function." (PMID 38411744, 2024). "The study proposes a novel paradigm for targeting acetate metabolism in cancer, wherein ACSS2 inhibition serves a dual purpose of impairing tumor cell metabolism and potentiating antitumor immunity." (PMID 39351241, 2024). "In conclusion, our data demonstrate the critical role of the ACSS2 gene in acetate-induced tumour cell survival under low pH and stellate cell-induced tumour burden in vivo." (PMID 38429478, 2024). "ACSS2 has been shown to play a critical role in tumor cell growth in various cancers, including breast and brain cancers." (PMID 38818373, 2024). "We observed an increase in the expression of ACSS2 in acidic regions of the tumour compared to tumour areas with normal pH." (PMID 38429478, 2024). "Treatment of ex vivo MDA-MB-231BR or 4T1BR tumor bearing brain slices with ACSS2 inhibitors AD-5584 and AD-8007 significantly reduced tumor growth of preformed tumors, suggesting induction of cell death compared to controls." (PMID 38818373, 2024). "Oral acetate supplementation also augments in vivo HCT116 and HT29 flank tumor growth and metastases, which likewise decreases significantly when Acss2 or HIF-2 signaling is impaired." (PMID 36862715, 2023).
tumor (continued). "It has been proven through in vitro and in vivo experiments that ACSS2 plays an important role in tumor cell survival under hypoxia in lung cancer, breast cancer, melanoma, and colon cancer." (PMID 38060103, 2023). "In tumor cells, acetate activated pro-lipogenic genes through ACSS2 by increasing histone acetylation levels at these gene promoter regions." (PMID 37870960, 2023). "Acetic acid intake was also significantly decreased in ACSS2‐downregulated tumor cells, indicating that ACSS2 plays an important role in the process of tumor cells using acetic acid to synthesize acetyl‐CoA to maintain tumor growth and tumor energy metabolism." (PMID 36994237, 2023). "ACSS2 expression appears to be critical for promoting GB viability and tumor growth by increasing the processes of mitochondrial TCA cycle and lipogenesis." (PMID 37298093, 2023). "ACSS2 facilitates the acetyl-CoA synthesis to support tumor survival and proliferative phenotype under metabolic stress conditions." (PMID 37870960, 2023). "Supplementing mice with exogenous acetate augments HT1080 cell tumor growth and metastasis in an Acss2 and HIF-2 dependent manner." (PMID 36862715, 2023). "The authors further assert that tumour grade-correlated ACSS2 is a key enzyme required for this metabolic vulnerability and potential therapeutic target of tumours." (PMID 37490079, 2023). "The findings were notable for an decreased cytosolic to nuclear Acss2 ratio in tumor compared to benign samples, driven mainly by the absence or reduced presence of Acss2 immunoreactivity in the cytosol of tumor tissue samples." (PMID 36862715, 2023). "Tumor and benign tissue for each patient was mounted on a single slide, followed by immunohistochemistry to identify Acss2 protein." (PMID 36862715, 2023). "During the screening of functional genomes, ACSS2 was found to be a key gene for tumor cell growth during nutrition stress." (PMID 35740562, 2022). "This review summarizes the biological function of ACSS2, its relation to survival and prognosis in different tumors, and how ACSS2 mediates different pathways to promote tumor metastasis, invasion, and drug resistance." (PMID 35740562, 2022). "Acss2 phosphorylation at S659 was greatly increased in tumor tissues compared with the surrounding normal tissues and stimulated the nuclear translocation of ACSS2, which is considered a reliable prognostic marker for poor survival." (PMID 35798917, 2022). "Our analysis of TCGA dataset shows that only ACLY mRNA expression is significantly increased in tumor tissues compared with normal/benign tissues, whereas ACSS2 mRNA is expressed at the reduced levels in tumors samples." (PMID 36497382, 2022). "Currently, tumor metabolism remains a popular research topic, and the discovery of the function of ACSS2 has opened up a new direction for tumor metabolism research." (PMID 35798917, 2022). "The highly increased expression of ACSS2 in PRCCs suggests high tumor-specific acetate consumptions in these cells." (PMID 36142502, 2022). "By promoting the acetylation of histones and transcription factors, ACSS2 influences metabolic reprogramming and cell cycle progression in tumor cells." (PMID 35798917, 2022). "Research on the molecular mechanism by which ACSS2 mediates the occurrence and development of different tumors can provide us with new insights for understanding tumorigenesis and tumor development and identify new targets for molecular-targeted tumor therapy." (PMID 35798917, 2022). "ACSS2 in the nucleus can also promote the expression of tumor-related genes, thus promoting tumor growth, proliferation, invasion, and metastasis from various aspects." (PMID 35740562, 2022). "Accumulating studies show that hypoxia and a low serum level induce ACSS2 expression to help tumor cells cope with this nutrient-poor environment." (PMID 35740562, 2022).
tumor (continued). "In tumor cells, this reverse reaction catalyzed by ACSS2 produces less ATP than the forward reaction and thus serves mainly to maintain acetyl-CoA homeostasis in tumor cells." (PMID 35798917, 2022). "Among these five prognosis-related genes, we found that INHBA and CD24 were oncogenic genes, while GRAMD1C, NFKBIA and ACSS2 were tumour suppressor genes." (PMID 35999846, 2022). "The tumor cells expressing higher ACSS2 had a lower survival rate when the tumor was of the same grade." (PMID 35740562, 2022). "Acetyl-CoA Synthetase 2 (ACSS2) is highly expressed in a variety of tumors, which is very important for tumor growth, proliferation, invasion, and metastasis in the nutritional stress microenvironment." (PMID 35740562, 2022). "On the other hand, SREBP-2 targets ACSS2 to provide a growth advantage to cancer cells in the condition of the tumor microenvironment." (PMID 39086974, 2022). "Exogenous acetate further promotes HIF-2α acetylation, CBP/HIF-2α complex formation, and HIF-2 signaling, while tumor growth and metastasis in mice also increase in an ACSS2- and HIF-2-dependent manner." (PMID 35798917, 2022). "The higher the tumor stage, the more significant the difference in ACSS2 expression between normal tissue and tumor tissue." (PMID 35740562, 2022). "This article mainly reviews the mechanism of ACSS2-promoting tumor growth from many aspects and the prospect of clinical application of targeted inhibitors." (PMID 35740562, 2022). "ACSS2 is considered a target for tumor therapy and serves an important function in cell proliferation, gene expression regulation, and bioenergetics." (PMID 35798917, 2022). "Immunohistochemical results showed that ACSS2 was mainly located in the tumor nucleus in HCC tissues with positive ACSS2 expression." (PMID 35740562, 2022). "ACSS2 is a new target for future tumor therapy and a tool for the assessment of its therapeutic effects." (PMID 35740562, 2022). "Novel-specific inhibitors of ACSS2 are developed and confirmed to the effectiveness in pre-clinical tumor models." (PMID 35740562, 2022). "We next performed in situ proximity ligation assay between HIF1α and sXBP1 in human/mouse astrocytes and GBM tumour cells depleted of sXBP1 targets SREBP2/ACSS2." (PMID 34811795, 2022). "Tumor cells synthesize acetyl-CoA by uptake of extracellular acetic acid via acetyl coenzyme A synthetase 2 (ACSS2) to provide a carbon source for tumor cells." (PMID 34206705, 2021). "Our research intended to identify the correlations of ACSS2 with clinical prognosis and tumor immune infiltration in CESC." (PMID 34206705, 2021). "Small-molecule inhibitors VY-3-135 and VY-3-249 impair tumor growth in vivo in a breast cancer model that shows high ACSS2 expression and in a model of obesity-induced myeloma, respectively." (PMID 34203535, 2021). "From the TIMER database, we found a significant increase in ACSS2 expression in tumor tissues compared to normal controls in CESC." (PMID 34206705, 2021). "In agreement with the prognostic characteristics of the ACSS1 and ACSS2 enzymes it was seen in HCC subtype-specific GEMs that iHCC1 tumours favourably expressed ACSS2, iHCC2 tumours ACSS3, whereas iHCC3 tumours ACSS1 for acetate utilisation." (PMID 32201876, 2021). "Since cancer cells use acetate as a carbon source, ACSS2 is critical for tumor metabolism in a hypoxic and glucose-restricted environment, leading to a shift in metabolism from aerobic glycolysis to oxidative phosphorylation (OXPHOS)." (PMID 34206705, 2021). "We observed the declined expression of lipid homeostasis regulating molecules like FASN, ACSS2, and SREBP1c in MJ exposed tumor cells." (PMID 33718176, 2021). "Previous work has shown that tumor growth is reduced by suppressing ACSS2 expression in most cancers." (PMID 33937302, 2021).